LOX (lysyl oxidase)
Diseases named in the same sentence as LOX in open-access papers (continued):
Sharing a sentence is not in itself a finding about the gene and the disease.
tumor (continued). "MAOA (T; p = 0.005) and MAOB (T; p = 0.006) in tumor cells were higher in ACN, whereas LOX was higher in tumor cells (T; p < 0.001) and LOX in stromal cells (S; p < 0.001) and AOC3 in tumor cells (T; p < 0.001) were higher in PCC." (PMID 37509535, 2023). "LOX acts on VEGF induction and HIF1α activation, and promotes tumor progression and metastasis, including OS." (PMID 37240338, 2023). "Studies have shown that ncRNAs carried by EVs can mediate the deposition of fibronectin (FN), collagen, MMPs, and lysyl oxidase (LOX) in the microenvironment of pre-metastatic organ to remodel the ECM and promote tumor cell adhesion and colonization." (PMID 37046819, 2023). "The mean H-scores of ACN in the tumor cells were MAOA 180.6, LOX 163.3, AOC3 46, and MAOB 24.4, and in stromal cells, they were LOX 142.1, MAOA 126.6, AOC3 26.7, and MAOB 3.1." (PMID 37509535, 2023). "Inter-tumor Core and Rim regions showed significantly higher relative expression of hypoxia response genes, including LDHA, VEGFA, LOX, PLAUR, SERPINE1, and IGFBP3." (PMID 37434262, 2023). "The remote control of PMN formation by the primary tumor secretome presents the opportunity for circulating PMN-inducing biomarker detection and monitoring (MMPs, TIMPs, LOX, and EVs) in liquid biopsies from patients." (PMID 37350937, 2023). "They showed that interfering with collagen crosslinking into fibers by inhibition of the lysyl oxidase (LOX) enzyme reduces ECM content and tumor stiffness, improving T cell migration and improving the efficacy of anti-PD-1 blockade." (PMID 37284199, 2023). "Considering that B and T lymphocytes are significant contributors of LOX, their involvement in ECM remodeling assumes greater significance, thereby emphasizing their critical role in the overall context of tumor advancement and metastasis." (PMID 38332915, 2023). "Roles of other immune cells, such as NKp46-expressing NK cells, LOX-expressing T cells and TGF-β/CD73/adenosine-dependent Myeloid cells in ECM remodeling and tumor progression are recently reported." (PMID 36906534, 2023). "Inhibiting lysyl oxidase (LOX)-mediated collagen crosslinking decreases tissue fibrosis and stiffness to reduce tumor incidence via β1 integrin-PI3K signaling." (PMID 37864030, 2023). "Interestingly, some of the common down-regulated genes, such as EPHA7 and NSUN7, are known for both their tumor suppressing and promoting roles, or are associated with overall survival (OS) (SLC22A31), while others have clear pro-tumorigenic roles (ADGRF1, LOX, LY6G5C, SNAI2, TNFRSF11B, ZNF233)." (PMID 36769365, 2023). "Overexpressed LOX was found to promote angiogenesis, and expression level of LOXL2 was higher in HCC than in non-tumor tissue." (PMID 35311155, 2022). "LOX and SNAI2 can regulate the induction of TIMP-4, which can lead to tumor invasion, migration, and VEGF expression." (PMID 35954348, 2022). "Concurrently, the Hic-5 accumulated in the nucleus of fibroblasts induced LOX expression, which increased ECM stiffness and accelerated tumor progression." (PMID 36293126, 2022). "(III) Low levels of methylation at some cg sites in the LOX gene were significantly related to poor OS and PFS, and methylation levels of LOX are negatively correlated with advanced tumor stage." (PMID 36202905, 2022). "Further analysis suggested that LOX and LOXL3 strongly correlated with tumor-infiltrating lymphocytes (TILs), various immune signatures, and immune checkpoints." (PMID 35433829, 2022). "TCGA database analysis revealed that LOX and IFI44 mRNA expressions were higher in ESCA tumor tissues, while IL18 and SLURP1 mRNA expressions were higher in normal tissues." (PMID 36090891, 2022). "Cancer cells secrete LOX to promote the cross-linking of collagen and elastin in the ECM and to prepare a suitable environment for the metastasis of tumor cells." (PMID 36419894, 2022).
tumor (continued). "NACT is known to stimulate CAF recruitment, leading to increased tumor ECM density and stiffness through excess stromal protein and lysyl oxidase (LOX) production." (PMID 35205605, 2022). "The multifaceted approach aimed to exploit the intrinsic therapeutic activity of targeting LOX in the tumour ECM and selectively accumulate epirubicin within the tumour site with reduced systemic toxicity." (PMID 36678741, 2022). "LOX family members, in particular LOX and LOXL2, are also involved in tumor progression through extracellular and intracellular actions." (PMID 35267510, 2022). "Similar to the results of IHC, qRT‐PCR and H&E staining, LOX and COL1A1 expressions and tumour infiltration increased in vivo when GBM cells (X01 cells) were co‐injected with MSLCs rather than when injected alone." (PMID 35908277, 2022). "Paclitaxel (PTX) chemotherapy enhanced rapid ECM remodeling and mechanostructural changes in the lungs of tumor-free mice, and the protein expression and activity of the ECM remodeling enzyme lysyl oxidase (LOX) increased in response to PTX." (PMID 34666995, 2022). "Along these lines, inhibition of lysyl oxidase (LOX)-mediated collagen crosslinking decreases focal adhesions, reduces PI3K activity, and impedes tumor progression in mice." (PMID 36158191, 2022). "Next, collagens in interstitial matrix were linearized by tumor-derived lysyl oxidase (LOX), which created migratory tracks used for the migration of the tumor cells." (PMID 35915456, 2022). "In combination with these antibodies, radiofrequency ablation (RFA), along with hemin and LOX co-loaded CaCO3-encapsulated PLGA nanoreactors, can enhance anti-tumor immunity and inhibit tumor growth." (PMID 36560459, 2022). "In particular, we noticed that COL1A2, LAMB3, LOX, LTBP2 and S100A6 were significantly upregulated in tumor specimens, when compared with normal tissue." (PMID 35340765, 2022). "It was then found that the enhanced cross-linking of collagen by lysyl oxidase induces integrin clustering in focal adhesions that, in turn, enhances PI3K signaling, which subsequently induces tumor cells invasiveness." (PMID 35682926, 2022). "Further, analysis of the association between those ECM components and GC clinicopathological features revealed that increased expression of COL1A2, LOX and LTBP2 significantly correlated with high tumor stage." (PMID 35340765, 2022). "The primary tumor secretes different factors—such as CCL2, IL6, lysyl oxidase (LOX) and DKK1—into the circulation to create a pre-metastatic niche in the bone by altering the bone microenvironment." (PMID 36497192, 2022). "The LOX and LOX-like (LOXL) proteins also have a variety of biological functions, such as development and growth regulation, tumor suppression, and cellular senescence." (PMID 36146878, 2022). "Consistent with what we observed for LOX and LTBP2, we found that COL10A1, which was the only tumor-specific protein, is strongly increased in tumor tissue (p = 5.93e-06), when compared with paired normal adjacent mucosa." (PMID 35340765, 2022). "Further ssGSEA revealed that compared to tumours with low circNEIL3 expression, tumours with high circNEIL3 expression exhibited higher levels of CCL2 and LOX." (PMID 35031058, 2022). "Several of these genes, in particular lysyl oxidase (LOX) and lysyl oxidase like-2 (LOXL2) were identified as genes that are upregulated by hypoxia, and promote tumor cells invasion and metastasis." (PMID 35682926, 2022). "In mouse models of breast cancer, it was recently shown that expression of LOX in CD8+ T cells resulted in ECM remodelling in the lungs and enabled seeding for circulating tumour cells." (PMID 35713387, 2022). "Secreted lysyl oxidases, such as LOX and LOXL2, also influence the spread of tumor cells to distant sites by another mechanism." (PMID 35682926, 2022).
tumor (continued). "The expression of CSE1L, LOX, RHBDD1, RRBP1 and SOGA1 was significantly higher in tumors than in tumor-adjacent tissue, and the survival analysis of each gene reached the same conclusion." (PMID 36421795, 2022). "Seven genes of the prognostic model (COPA, GPX7, ITGB5, MATN3, MCM7, MMP1, and SPP1) have been validated to be related to tumor progression, whereas the remaining three genes, BNDF, GADD45B, and LOX, need to be further analyzed." (PMID 35699863, 2022). "LOX (lysyl oxidase) was identified as a hypoxia-responsive gene and found it to be regulated HIF-1, and hypoxia-induced LOX played a key role in tumor metastasis." (PMID 36483920, 2022). "Compared to adjacent pancreas tissues, we found higher mRNA expression of LOX in PDAC tissues, which was correlated with tumor stage and grade of PDAC." (PMID 35433829, 2022). "Specifically, the increased expression of LOX, LOXL1 and LOXL2 appears to be correlated with similar trends in terms of patient survival, tumour infiltrates and correlation with expression of genes involved in tumour-related processes." (PMID 35800439, 2022). "The LOX inhibitor ethyl 3,4-dihydroxybenzoate (EDHB) was found to decrease tumor fibrosis and metastasis in a MDA-MB-231 xenograft model." (PMID 34769066, 2021). "To clarify the correlation between LOX expression and the immune microenvironment, we used the CIBERSORT method to analyze the proportion of 22 immune cell subpopulations in tumor infiltration." (PMID 34595188, 2021). "Once the tumor structure and mechanical properties of each model were characterized, an ECM-targeting therapy dependent on LOX inhibition with BAPN was tested." (PMID 34106045, 2021). "The immunofluorescent staining of our local clinical tumor tissue section analyses also showed that the expression of YAP1, LOX, CD68 (human macrophage marker), SPP1, and PD-L1 was enhanced in HSPA7-high GBM tissues compared to HSPA7-low tissues." (PMID 34354698, 2021). "When tumors reached 7.0 ± 0.5 mm in diameter, tumor lysates of mice with MDA-MB-231 tumors, MDA-MB-231 tumors treated with LOX inhibitor, and MCF-7 tumors were collected and treated with LS-AuNPs." (PMID 34572752, 2021). "The localization of LOX to the ECM, especially in cancer cells, makes it an attractive target for activated prodrugs that tend to accumulate in the tumor stroma." (PMID 34815382, 2021). "Reducing LOX-mediated collagen crosslinking decreased focal adhesions and PI3K activity, hampered malignancy, and lowered tumor incidence." (PMID 33658580, 2021). "Specifically, the authors used fresh tumor slices from mice treated with beta-aminopropionitrile (BAPN), a lysyl oxidase (LOX) inhibitor regulating collagen fiber stabilization." (PMID 34638476, 2021). "Tumor-derived exosomes remodel the ECM by accumulating fibronectin and promoting ECM-modifying enzyme lysyl oxidase (LOX) crosslinking to enhance the adhesion of the bone-marrow-derived cells which are essential pre-metastatic niche components." (PMID 33805398, 2021). "Lysyl oxidase inhibition has also been shown to improve delivery, as lysyl oxidase, discussed earlier, is responsible for cross-linking the ECM proteins and thus increasing the tumor stiffness." (PMID 33572559, 2021). "The qRT-PCR results also showed that the mRNA expressions of COL I, COL III, LOX, and LOXL2 in tumor tissues were higher than those in normal tissues." (PMID 34335820, 2021). "In the primary tumor, ECM stiffness characterized by lysyl oxidase (LOX)-mediated collagen crosslinking forms a physical barrier and influences drug penetration to tumor cells." (PMID 34300195, 2021). "In contrast to LOX and AKAP12, we found that MAFF transcriptionally regulates a different set of target genes to promote tumor invasion and metastasis." (PMID 34262028, 2021).
tumor (continued). "Despite minor effects in primary tumor growth upon LOX inhibition or PD-1 blockade treatment alone, their combination increases effector CD8 T cell accumulation in tumors and significantly delays tumor progression in a pancreatic cancer model." (PMID 34106045, 2021). "LOXL1, like other Lysyl oxidase (LOX) family members, has an established role in modifying the tumor microenvironment by crosslinking collagens and elastin in the extracellular matrix." (PMID 33790946, 2021). "LOX- and LOXL2-mediated tumour progression is due primarily to ECM modifications but relies in part on intracellular signalling." (PMID 33544155, 2021). "Growth factors like TGFβ, HGF, FGF and EGF enhance tumor cell invasiveness and induce EMT as well as extracellular matrix modulating factors like lysyl oxidase (LOX)." (PMID 33472580, 2021). "In breast, nasopharynx, gastric, pancreatic, pulmonary, renal, lung, ovarian, and thyroid cancers, lysyl oxidase and collagen were found to influence the architecture of the ECM, creating a favorable microenvironment for tumor development and progression." (PMID 33669630, 2021). "The goal of this work was to develop a lipid-based vesicle that simultaneously exploits the intrinsic therapeutic activity of targeting LOX in the tumor ECM and selectively concentrates epirubicin at the tumor site, with minimal systemic toxicity." (PMID 33658580, 2021). "Newly deposited ECM further supports for the reorientation of collagens and other ECM fibers by the cross-linking through LOX and transglutaminase, generating larger and stiffer ECM fibers along with enlargement of the tumor tissue." (PMID 34821729, 2021). "The LOX inhibitor β-aminopropionitrile (BAPN) was used to block LOX expression in the MMTV-PyMT model, leading to decreased ECM stiffening and delaying tumor progression." (PMID 34769066, 2021). "In particular, necrotic tumor cells were 5% in the control group, 25% in Lipo-LOX, 50% in Lipo-EPI, 20% in free EPI, and 60% in Lipo-EPI-LOX treated tumors." (PMID 33658580, 2021). "Previous studies have shown that overexpression of LOX and LOXL2 can increase the abnormal crosslinking of collagen, promote fibrosis remodeling, and accelerate the malignant progression of the tumor." (PMID 34335820, 2021). "The MIR4435-2HG- and ELFN1-AS1-associated ceRNA subnetworks affected and regulated the expression of the COL5A2, LOX, OSBPL3, PLAU, VCAN, SRM, and E2F1 target genes and were found to be related to prognosis and tumor-infiltrating immune cell types." (PMID 33750326, 2021). "Further analysis demonstrated that higher mRNA expression of LOX and LOXL2 were significantly correlated with poor survival, tumor grade, individual cancer stages, and nodal metastasis status." (PMID 32970930, 2020). "A recent study indicated that ATP7A plays essential roles in loading lysyl oxidase (LOX) and LOX-like (LOXL) proteins, which have well-documented roles in tumor metastasis." (PMID 32709883, 2020). "Lysyl oxidase (LOX) is an extracellular amine oxidase and regulator of tumor microenvironment through ECM posttranslational modification which promotes tumor cell proliferation." (PMID 32467737, 2020). "LOX enzymes assist in cross-linking fibril collagens in the ECM; the cross-linking of fibril collagens greatly contributes to overall tumor stiffness." (PMID 32850332, 2020). "Overall, these results confirm the concurrent gene upregulation of LOX, COL1A1, senescent cells, and CAFs markers in tumor tissues and in particular in those with BRAF-like signaling." (PMID 31906302, 2020). "In normoxic LOX tumor xenografts, infusion of T-state PolyhHb led to a significant increase in RBF to the tumor compared to baseline." (PMID 32647211, 2020). "Li and colleagues demonstrated a novel function of a member of the lysyl oxidase (LOX) family of proteins, LOXL4, in HCC exosome-mediated tumor metastasis, identifying a new promising therapeutic target for HCC." (PMID 31973229, 2020).
tumor (continued). "Tumor grade and individual cancer stages in KIRC were also significantly affected by higher protein expression of LOX and LOXL2 from CPTAC samples." (PMID 32970930, 2020). "In our future research, we need to construct cell lines that differently expressed LOX and LOXL2 to verify our research results from the aspects of in vivo, in vitro and KIRC tumor tissue." (PMID 32970930, 2020). "Tumor stage-dependent effects would also be expected for several agents used to manipulate the ECM, since many such agents (e.g., LOX inhibitors) block only progressive ECM remodeling, and do not reverse previous activity." (PMID 32434573, 2020). "LOX and LOXL2 were significantly over‐expressed in KIRC tumor compared to normal tissue using GEPIA." (PMID 32970930, 2020). "Lysyl oxidase-like 2 (LOXL2) is a member of the lysyl oxidase (LOX) gene family, which plays an important role in development, senescence, tumor suppression, cell growth, and chemotaxis." (PMID 32621591, 2020). "This evidence suggested that TGF-β, PDGF, IL-1β, and SDF-1 induce a Hic-5-rich CAF phenotype which drives the overexpression of LOX and collagen to increase the ECM stiffness and generate a tumor-permissive stroma." (PMID 31650200, 2020). "Overexpressed mRNA of LOX and LOXL2 were significantly correlated with tumor grade, individual cancer stages and nodal metastasis status in KIRC from TCGA samples." (PMID 32970930, 2020). "Accordingly, inhibition of LOX and of LOXL2 significantly reduces tumor growth and metastasis in various cancer models." (PMID 31130685, 2019). "LOX and LOXL2 activities have been also shown to create a favorable environment for cell invasion and subsequent tumor growth at metastatic sites." (PMID 31540259, 2019). "Both LOX and LOXL2 have been positively involved in neovascularization, although most of the approaches were focused on tumor angiogenesis." (PMID 31615160, 2019). "After LOX inhibition, we analyzed the effects on protein expression and enzyme activity of MMP-2 and MMP-9 in tumor tissues from the nude mouse model." (PMID 31777578, 2019). "In order to confirm the relationship between LOX and MMP-2 and MMP-9 in tumorigenesis and tumor progression, we studied LOX, MMP-2, and MMP-9 in human tumor tissues, animal models, and in vitro cell culture." (PMID 31777578, 2019). "Within this family, LOX is the most characterized member and LOX‐L2 (lysyl oxidase homolog‐2) has been comprehensively documented to participate in ECM remodeling of the tumor and fibrotic microenvironments." (PMID 30538116, 2019). "Further, overexpression of both LOX and LOXL2 increased tumor perfused vessel density in different syngeneic models." (PMID 31615160, 2019). "The authors showed that chemical or antibody inhibition of LOX prevented collagen remodeling and increased ECM stiffness, resulting in increased tumor latency, decreased tumor volume, and abrogated malignant transformation." (PMID 31130685, 2019). "Importantly, it has been well documented that, the increased matrix rigidity induced by hypoxia due to LOX-mediated collagen fiber cross-linkage also contributes to aberrant neovasculization with an abnormal hierarchical arrangement of vascular structures that further promotes tumor metastasis." (PMID 31861892, 2019). "The relationship between LOX and MMP-2 and MMP-9 in tumorigenesis and tumor progression are still unclear." (PMID 31777578, 2019). "The results of this study show that LOX can upregulate PDGFR during tumorigenesis and tumor progression to affect the PDGF-PDGFR signaling pathway." (PMID 31777578, 2019). "Other cell types within the tumor stroma such as immune cells and tumor cells can also impact ECM remodeling either directly (e.g., secretion of MMPs, LOX, or collagenases) or indirectly (e.g, secretion of growth factors and cytokines that activate CAFs)." (PMID 31144616, 2019).